CRP (C-reactive protein)
Diseases named in the same sentence as CRP in open-access papers (continued):
Sharing a sentence is not in itself a finding about the gene and the disease.
Cholecystitis (35 papers, 2008 to 2026). The presence of inflammatory changes in the gallbladder. "In patients with chronic cholecystitis, 53% of CRP variability was explained by the presence of independent variables, including age, hemoglobin (Hb), hematocrit (HT), amylase, CA19-9, and CEA (adjusted R2 = 0.530; p = 0.004)." (PMID 40332145, 2025). "Patients with CRP ≥ 3 mg/dL were most likely to have complicated cholecystitis, with a probability of 0.85 (36%)." (PMID 40722527, 2025). "The stepwise regression analysis demonstrated that the combination of clinical and laboratory parameters, including AST, ALT, amylase, and tumour markers like CA 19-9, provided a strong predictive model for CRP levels in patients with chronic cholecystitis." (PMID 40332145, 2025). "Preoperative NLR and CRP values can serve as indicators to detect cholecystolithiasis with cholecystitis in elderly patients." (PMID 38012600, 2023). "The optimal cutoff value of the CRP in diagnosing Cholecystitis was 13.05 (95% CI, 0.9284–0.9830; P < 0.001)." (PMID 38012600, 2023). "The study found that a preoperative NLR cutoff value of 2.995 and a CRP cutoff value of 13.05 can distinguish the occurrence of the disease in elderly patients with cholecystolithiasis with cholecystitis." (PMID 38012600, 2023). "This study suggests that preoperative NLR and CRP values can serve as a simple method for identifying the severity of cholecystitis in elderly patients with cholecystolithiasis." (PMID 38012600, 2023). "This study aims to assess the effectiveness of neutrophil/lymphocyte ratio (NLR) and C-reactive protein (CRP) in diagnosing cholecystolithiasis with cholecystitis in elderly patients." (PMID 38012600, 2023). "This study aims to evaluate the predictive value of preoperative NLR and CRP levels in elderly patients with gallstones with cholecystitis and to determine the corresponding NLR value that can distinguish between different severities of the condition." (PMID 38012600, 2023). "CRP levels above 198.95 mg/L have been shown to be predictive of grade 3 cholecystitis, whereas CRP levels between 198.95 mg/L and 70.65 mg/L have been shown to be predictive of grade 2 cholecystitis." (PMID 35334564, 2022). "The CRP threshold of 70.65 mg/L for grade 2 cholecystitis has been shown to have a sensitivity of 75% and specificity of 95%, and histopathological findings have shown that CRP has better sensitivity than WCC count for cholecystitis." (PMID 35334564, 2022). "Advanced age, male gender, severe cholecystitis, higher BMI, elevated CRP or WBC, incarcerated stones in the gallbladder neck, and thick gallbladder wall are few factors that led to prolonged operation time as well as conversion to open surgery." (PMID 36726949, 2022). "Multivariate regression analysis showed that patient’s age (OR=1.047; p=0.003), higher CRP (OR=1.005; p=0.012) and NLR (OR=1.094; p=0.047) were significant independent factors associated with severity of cholecystitis." (PMID 33796428, 2021). "On the contrary, some studies suggest that the serum level of CRP is positively related to the severity grading of cholecystitis." (PMID 31358829, 2019). "Raised white blood cell count and C-reactive protein are frequent findings especially with the onset of gangrenous cholecystitis." (PMID 18294374, 2008). "CRP also performs well in severe cases but lacks specificity in mild cholecystitis." (PMID 40067493, 2025). "The diagnostic value of NLR and CRP was determined by using the Receiver Operating Characteristic Curve (ROC), and the optimal value of preoperative NLR related to the severity of elderly patients with cholecystolithiasis with cholecystitis was identified." (PMID 38012600, 2023). "A mean CRP of 17mg/L has been derived from grade 1 cholecystitis patients." (PMID 35334564, 2022). "However, there is clinical opinion that WCC is preferable for distinguishing between cholecystitis and BC, as CRP levels will be raised in both, and they can be distinguished with other features." (PMID 35334564, 2022).
Cholecystitis (continued). "C Reactive Protein (CRP) levels may be high in bone crises (bone infarction) or infectious complications (cholecystitis more common in GD)." (PMID 28218669, 2017). "However, the median values of blood laboratory data, such as white blood cell count and total bilirubin, aspartate aminotransferase, alanine aminotransferase, alkaline phosphatase, and C-reactive protein levels, were significantly higher in the cholecystitis group." (PMID 35328274, 2022). "This study found that for elderly patients with cholecystolithiasis with cholecystitis, preoperative NLR and CRP levels can be used to distinguish the condition." (PMID 38012600, 2023). "The values of WCC, CRP, and NLR were significantly higher in elderly patients with gallbladder stones with cholecystitis compared to the control group (P < 0.001)." (PMID 38012600, 2023). "There are some biomarkers that can predict the severity of cholecystitis, such as WBC, C-reactive protein (CRP), and procalcitonin (PCT)." (PMID 34691290, 2021). "As per the Tokyo guidelines, diagnosis of acute cholecystitis requires the presence of signs of local inflammation (Murphy’s sign or RUQ pain/mass/tenderness) and systemic inflammation (fever, elevated C-reactive protein [CRP], or elevated WBC count) confirmed by imaging findings of cholecystitis." (PMID 40416234, 2025). "More severe cases of cholecystitis (gallstones without cholecystitis vs. mild vs. severe) exhibited significantly and consistently higher LC, NC, and CRP median values." (PMID 40067493, 2025).
chronic lung disease (35 papers, 2018 to 2025). According to the definitions of the American and British Thoracic Societies, including pulmonary functional tests, X-rays, and CT scans for items such as fibrosis, bronchiectasis, bullae, emphysema, nodular or lymphomatous abnormalities. "In a multivariable logistic regression analysis, prescribing for RTIs was independently and positively associated with COPD/chronic lung disease, purulent/bloody sputum, an abnormal chest X-ray, and CRP ≥ 100 mg/L." (PMID 34223137, 2021). "Prescribing for RTI was independently and positively associated with COPD/chronic lung disease, purulent/bloody sputum, abnormal chest X-ray, and CRP ≥ 100 mg/L." (PMID 34223137, 2021). "On the other hand, circadian clock disruption during chronic lung diseases has essential effect in augmented oxidative stress and increased systemic inflammation, as evidenced by increased interleukin-6, C-reactive protein, and tumor necrosis factor." (PMID 38225649, 2024). "The two groups were comparable in terms of chronic renal disease, chronic lung disease, smoking status, level of hemoglobin, creatinine, low density lipoprotein, thyroid stimulating hormone, and CRP." (PMID 36557074, 2022). "Neutrophilic inflammation is a common feature of many chronic lung diseases, and other cytokines including C-reactive protein (CRP) may contribute to neutrophil recruitment and increased inflammatory response." (PMID 36363728, 2022). "It was observed that many patients had a long hospitalization associated with chronic lung disease, liver damage, Roma ethnicity, a long duration elapsed from the last MMR dose, elevated c-reactive protein, the presence of bilateral pulmonary condensations on X-ray, and elevated procalcitonin." (PMID 36145449, 2022). "During the unadjusted evaluation, older age, history of chronic lung disease, higher admission neutrophil to lymphocyte ratio, urea, C reactive protein, lactate dehydrogenase, and aspartate transaminase were associated with both severe and 7-month all-cause mortality." (PMID 36699557, 2022). "Inflammatory biomarkers, such as C-reactive protein (CRP), interleukins 1 and 6 (IL-1 and IL-6), and tumor necrosis factor-alpha (TNF-α) have all been reported to be increased in the circulation of the elderly and patients with chronic lung disease." (PMID 40729030, 2025). "Candidate variables for the first multivariable model were: age ≥ 60 years, sex, chronic lung disease, active cancer, BMI, LMWH administration, D-dimer at admission ≥ 1,000 ng/mL, C-reactive protein at admission ≥ 150 mg/L, ICU admission, worst PaO2:FiO2, and peak D-dimer ≥ 6,000." (PMID 32984388, 2020). "After precisely analyzing the CRP and ESR levels in 75 participants, we confirmed that the random number (RN) 48 had an abnormally elevated HS-CRP value after eight weeks due to severe shin inflammation and RN 46 had an abnormally elevated ESR value due to chronic lung disease." (PMID 36998613, 2023). "A greater proportion of the non-survivors had chronic lung disease, shock, and invasive mechanical ventilation (IMV); a higher respiratory rate, LDH, CRP, and CAR; and significantly lower CD8+ T lymphocyte counts (all P < 0.001)." (PMID 36424963, 2022).
hyperhomocysteinemia (35 papers, 2013 to 2025). A serious metabolic condition caused by mutations in the MTHFR gene, medications, or nutritional deficiency. "Hyperhomocysteinemia, elevated lipoprotein(a) and high C-reactive protein (CRP) are lipid-independent risk factors for cardiovascular diseases." (PMID 35268083, 2022). "The baseline features of samples by dividing into two groups (normal and hyperhomocysteinemia) to describe the association between C reactive protein (CRP) and homocysteine (HCY)." (PMID 26367537, 2015). "In a study conducted 34 that hyperhomocysteinemia (HHcy) is a risk factor for severe LA and is associated with high hs-CRP levels, suggesting that the effect of Hcy on LA may involves inflammatory responses, but the exact mechanism still needs further study." (PMID 38903919, 2024). "Patients in the quartile quarter 4 more often had elevated CRP, hyperhomocysteinemia, and an elevated serum LDL than the patients in the other groups." (PMID 37400826, 2023). "In a 5-year follow-up study, participants with elevated homocysteine or C-reactive protein (CRP) levels demonstrated a decrease in IC, and this decrease was more significant among those exhibiting higher CRP levels combined with hyperhomocysteinemia." (PMID 35371613, 2022). "Plasma C-reactive protein level and hyperhomocysteinemia should be considered as a prognostic factor in CVST." (PMID 33375456, 2020). "In the present study, we observed that AP patients in the hyperhomocysteinemia group possess significantly higher C-reactive protein levels than the control group." (PMID 32090108, 2020). "The total antioxidant capacity (TAC), homocysteinemia, C-reactive protein (CRP), alpha-1-acid glycoprotein (AGP), waist circumference (WC) and cholesterol intake, based on methodological protocols for different morbidities, LDL-C levels were correlated with these variables." (PMID 33326437, 2020). "Hyperhomocysteinemia could induce changes in mRNA and protein expression of CRP in vascular smooth muscle cells via the NMDAr-ROS-ERK1/2/p38-NF-κB signal pathway." (PMID 28377713, 2017). "Individuals with a homozygous mutant substitution in MTHFR have been shown to have elevated C-reactive protein (CRP), fibrinogen, and white blood cell (WBC) count, suggestive of systemic inflammation related to hyperhomocysteinemia." (PMID 39408801, 2024).
leukemia (35 papers, 2015 to 2025). A malignant (clonal) hematologic disorder, involving hematopoietic stem cells and characterized by the presence of primitive or atypical myeloid or lymphoid cells in the bone marrow and the blood. "Higher CRP levels are known to be associated with shortened leukemia-free and overall survival in univariate analyses, whereas for albumin, a prognostic value independent of several DIPPS-based scoring systems has been described previously." (PMID 36900271, 2023). "Although CRP is not thought to be directly associated with AML and chronic myeloid leukemia (CML), complications associated with leukemia, such as infections, and elevated systemic cytokines, such as IL-6, lead to elevated CRP levels." (PMID 29202702, 2017). "In the context that elevated CRP levels have been shown to be associated with shortened leukemia-free survival in myelofibrosis, it is of interest that our model was excellently validated by data on CRP levels in the different MPN disease stages as well." (PMID 28859112, 2017). "A high CRP and low pentraxin 3 were linked to a high risk of thrombotic events in PV and in ET, and a high CRP was associated with shortened leukemia-free survival in MPN patients with myelofibrosis." (PMID 26538820, 2015). "A prospective, population-based cohort study with a two-year follow-up revealed that an increasing CRP trajectory pattern was associated with a heightened risk of various cancers, including lung, breast, leukemia, bladder, stomach, colorectal, liver, gallbladder, and extrahepatic bile duct cancer." (PMID 41409302, 2025). "Elevated CRP levels have been associated with several adverse disease features and a shorter leukemia-free survival, and albumin has been consistently shown to add additional prognostic information independently of DIPSS and several DIPSS-based prognostic scoring systems." (PMID 36900271, 2023). "CRP was also associated with shortened leukemia-free survival in myelofibrosis." (PMID 35626232, 2022). "Elevated serum CRP levels are associated with poor prognosis in solid tumors, probably as an indicator of chronic inflammation associated with tumor progression, but the role of CRP in leukemia is unclear." (PMID 29202702, 2017). "Disease activity assessment in RA using inflammatory markers such as C-reactive protein (CRP) and erythrocyte sedimentation rate (ESR) provides essential insights into disease severity and potential leukemia risk." (PMID 41141147, 2025). "CRP retains perfect sensitivity for culture-proven infection (100% at >40 mg/L; Santolaya 1994) but exhibits reduced specificity in leukemia cohorts (66.7% at ≥105 mg/L; Baraka 2018)." (PMID 40647525, 2025). "Some of these studies also assessed CRP levels in leukaemia relapse episodes, which were generally much lower than 100 mg/L." (PMID 32209087, 2020). "Previous studies on longitudinal CRP analyses in leukaemia patients have included 20–63 patients and our study is the first to assess PA." (PMID 32209087, 2020). "Smaller studies of longitudinally measured CRP in leukaemia patients (n = 20–63) found that CRP levels > 100 mg/L correlated temporally with infectious episodes." (PMID 32209087, 2020). "In leukaemia patients, we have only encountered few longitudinal studies on CRP levels, all with 63 patients or less." (PMID 32209087, 2020). "Another recent study found that CRP trajectories play a crucial role in the occurrence of cancers, particularly in the lung, breast, bladder, stomach, colorectal, liver, and gallbladder and extrahepatic bile duct cancer, and leukemia." (PMID 37873776, 2023). "Patients with higher CRP levels had shorter leukemia-free survival (LFS, P = 0.041)." (PMID 35558519, 2022). "Furthermore, a higher CRP level correlated with a higher incidence of leukemia transformation." (PMID 35558519, 2022).
leukemia (continued). "In another study, nCD64 was found to have a sensitivity of 71.06% and a specificity of 91.46%, which was superior to CRP, PCT, and neutrophil percentage, as an indicator of infection in patients with leukemia combined with bacterial infection." (PMID 39559703, 2024). "(2018) found that neutrophil percentage in leukemia combined with bacterial infection had a sensitivity of 59.25% and a specificity of 85.36%, which was lower than CD64, CRP, and PCT, both in terms of sensitivity and specificity." (PMID 39559703, 2024). "Biochemical markers like elevated lactate dehydrogenase (LDH), C-reactive protein (CRP), platelets (PLT), and hemoglobin (HB) can indicate leukemia but lack specificity and can result in false positives." (PMID 39134989, 2024). "We found that the statistical association between CRP and the progression of MDS to leukemia was independent of other variables in the scoring system." (PMID 36114519, 2022). "In contrast, CRP, ESR, or WBCs allowed no robust differentiation of SJIA from neither of the three major differential diagnoses in suspected SJIA, i.e., infections, SIDs, and leukemia." (PMID 37878193, 2023).